SMAD4 (SMAD family member 4)
Diseases named in the same sentence as SMAD4 in open-access papers (continued):
Sharing a sentence is not in itself a finding about the gene and the disease.
pancreatic cancer (continued). "However, when combined with the oncogenic KrasG12D mutation, Smad4 deletion dramatically accelerated the development of pancreatic tumors, leading to a significant reduction in survival." (PMID 38666907, 2024). "Since the cooperation between SOX4 and KLF5 has been suggested as a molecular mechanism that drives tumorigenesis in SMAD4 defect pancreatic cancer cells, we postulated that Ep_VGLL1 represents cancer cells in SMAD4-deficient oncogenic processes driven by TGF-β." (PMID 38297291, 2024). "The observed effects of Smad4 loss on pancreatic weight, influenced by genetic background and sex, underscore Smad4’s regulatory role in pancreatic physiology and its potential impact on susceptibility to conditions like pancreatic cancer." (PMID 39596873, 2024). "It is worth mentioning that SMAD4 mutation often occurs at the late stage of pancreatic cancer, therefore, SMAD4 mutation may be used for the diagnosis of advanced precancerous lesions." (PMID 37304241, 2023). "In addition, it can also inhibit the progression of SMAD4-deficient pancreatic cancer by enhancing AMPK-mediated phosphorylation and ubiquitination degradation of HNF4G protein, providing the possibility of targeted therapy for pancreatic cancer." (PMID 38012210, 2023). "In pancreatic cancer, low SMAD4 expression is associated with malignant progression." (PMID 38003265, 2023). "Thus, our results indicated that loss of Smad4 in murine pancreatic cancer cells promoted tumor cell growth in vitro but paradoxically inhibited tumor growth in vivo, likely by engaging T cell‐mediated antitumor immunity." (PMID 35064757, 2022). "In addition to high‐frequency mutation in pancreatic cancer, Smad4 is also inactivated or mutated at varying frequency in breast, colorectal and gastric cancer." (PMID 35064757, 2022). "The mutations in SMAD4 are well-known to be important in pancreatic cancer." (PMID 36469540, 2022). "Upregulation of autophagy has been identified in SMAD4 mutated or deleted pancreatic cancer cells." (PMID 34002944, 2021). "SMAD4 is the downstream of TGFβ signaling and mutations associated with this gene has been reported in colorectal cancer, head and neck carcinoma, seminoma germ cell tumors and pancreatic cancers." (PMID 34048444, 2021). "SMAD4, a tumor suppressor gene, is mutated or deleted in approximately 55% of pancreatic cancers." (PMID 34002944, 2021). "Because SMAD4 mutated or deleted pancreatic cancers have an increased reliance on autophagy for treatment resistance, we hypothesized that patients with SMAD4 tumor loss/mutation would derive the greatest benefit from autophagy inhibition with HCQ." (PMID 34002944, 2021). "However, very few studies have investigated the relationship between SMAD4 mutation and immunotherapy in pancreatic cancer." (PMID 34880877, 2021). "Also in adult patients, tumor mutations, such as in EGFR, BRCA1/BRCA2, and SMAD4 genes, decrease engraftment rates in adenocarcinoma, breast cancer, and pancreatic cancer, respectively." (PMID 33837665, 2021). "SMAD4 is an important tumor suppressor whose mutation occurs in around 50% of pancreatic cancers." (PMID 33867818, 2021). "Numerous studies proved that alteration of SMAD4 is closely associated with pancreatic cancer." (PMID 32781778, 2020). "Therefore, it is necessary for us to conduct further in-depth research on SMAD4 and its mutation-related mechanisms in pancreatic cancer." (PMID 31684910, 2019). "Inactivation of SMAD4 has been associated with a more aggressive phenotype of pancreatic cancer." (PMID 31377855, 2019). "Similarly, the loss of SMAD4 was also confirmed to be associated with metastasis of pancreatic cancer." (PMID 31417657, 2019).
pancreatic cancer (continued). "For example, a low level of microRNA-494 contributes to increasing the transcriptional activity of β-catenin and promoting the expression of Wnt, leading to pancreatic tumourigenesis via the regulation of stem-cell renewal and induction of EMT in SMAD4-deficient pancreatic cancer cells." (PMID 31684910, 2019). "Therefore, the accumulation of SMAD4 mutations and deletions in pancreatic cancer obstructs the tumor-suppressive element, but enhances the pro-tumorigenic effect of TGFβ." (PMID 31569425, 2019). "Mutations of KRAS might be used to detect pancreatic cancer in early stage and SMAD4 mutations associate with dismal prognosis of pancreatic neoplasia." (PMID 29423035, 2018). "Therefore, it seemed particularly interesting to evaluate a possible cooperation between KRAS mutation and SMAD4 loss in favoring the progression of pancreatic cancer." (PMID 29156578, 2017). "Next, we checked the effect of IPP-14 on Smad4-deficient Capan-1 (human pancreatic cancer cells)." (PMID 28423593, 2017). "Clinical research results show that SMAD4 inactivation by mutations could be used as a prognostic biomarker in pancreatic cancers." (PMID 28452926, 2017). "The gene loss of SMAD4 was prominent in the pancreatic cancer." (PMID 27556634, 2016). "For example, restoration of canonical TGF-β signaling in SMAD4-deficient pancreatic cancer cells (PCCs) has been reported to suppress angiogenesis by up-regulating anti-angiogenic thrombospondin-1 (THBS1), and we detected a 5.63-fold increase in THBS1 in patients with a strong angiogenic signature." (PMID 26586478, 2016). "SMAD4 was shown gene copy number loss in nearly 30% of cases in pancreatic cancer from UTSW." (PMID 27929028, 2016). "In addition, SMAD4 is mutated in 50% of all human pancreatic cancers, supporting the important tumor suppressor role of the TGF-β pathway." (PMID 26078812, 2015). "We hypothesize that TGF-β pathway activation is common in pancreatic cancer and genetic variations of the pathway, plasma TGF-β1 level and tumor TGF-βR2 or SMAD4 expression are associated with clinical outcome of pancreatic cancer." (PMID 24465802, 2014). "Smad4 deficiency contributes greatly to the invasive phenotype of pancreatic cancer cells." (PMID 24587996, 2014). "Hahn and colleagues reported that about 90 percent of pancreatic carcinomas show allelic loss at chromosome 18q21.1, and further studies have confirmed that the SMAD4/DPC4 gene, localized to 18q21, was the target for 50% of the PDAC that exhibited 18q deletion." (PMID 24625091, 2014). "Likewise, in pancreatic cancer the tumors that grew in mice were more likely to have SMAD4 mutations and an independently developed metastatic gene signature." (PMID 23981300, 2013). "Moreover, the loss of Smad4 is associated with a higher likelihood of metastasis, poor outcome following surgical resection and predict a worse prognosis in patients with pancreatic cancer." (PMID 23588713, 2013). "Furthermore, missense mutations in the Smad2 and Smad4 genes occurring in colon and pancreatic cancer cells, respectively, have been reported to inhibit association of Smad2 with Smad4." (PMID 24386222, 2013). "Additionally, Smad4 is one of the most commonly inactivated genes in pancreatic cancer, and loss of p16 expression is observed in most pancreatic cancer." (PMID 22860091, 2012). "We generated EGFP- and DsRed-expressing batches of the Smad4-mutated BxPC3 pancreatic cancer cell line and determined whether such cells would perform cannibalism after Nupr1-depletion and TGFβ treatment." (PMID 22821859, 2012). "Although lost in many cancers, loss of Smad4 is more sensitive and specific to pancreatic cancer." (PMID 22195733, 2011). "A similar finding was also reported in Smad4 deletion-associated pancreatic cancer." (PMID 22204491, 2011). "SMAD4 is mutated in many cancers, including pancreatic cancer." (PMID 20684793, 2010).
pancreatic cancer (continued). "Interestingly, loss of SMAD4 in pancreatic cancer cells has been shown to shift TGFβ-triggered downstream cascades to mitogen-activated protein kinase (MAPK) and extracellular signal-regulated kinase (ERK) signaling, a pathway also known to be triggered upon CXCR4 activation." (PMID 39639824, 2025). "In pancreatic cancer specifically, patient-derived models such as organoids and xenografts have allowed for a more nuanced understanding of the tumor’s heterogeneity, offering insights into how genetic mutations, such as those in the Smad4 gene, contribute to tumor growth and resistance to therapy." (PMID 39596873, 2024). "Furthermore, inactivating mutations are commonly found in the SMAD4 gene in pre-malignant cancers such as pancreatic carcinoma, while SMAD4 has been reported as an essential gene for metastasis of breast cancer (Levy and Hill, 2006; Massagué, 2008; Massagué, 2012)." (PMID 35834310, 2022). "Collectively, these findings unveil a metabolic-transcriptional circuit wherein palmitoylation bridges lipid metabolism with SMAD4-driven oncogenesis, and posit SMAD4 palmitoylation as a therapeutic vulnerability in pancreatic cancer." (PMID 41885390, 2026). "In this study, we utilized molecular cytology techniques, animal models, and human pancreatic cancer tissues to investigate the role of FoxM1 in Smad4 stabilization and its regulation of TGF-β signaling." (PMID 41963301, 2026). "The involvement of FoxM1 in the TGF-β/Smad signaling pathway has been linked to pancreatic cancer progression; however, the mechanisms behind the cooperative regulation of TGF-β signaling by FoxM1 and Smad4 remain poorly understood." (PMID 41963301, 2026). "For pancreatic cancer cell lines, we have established two CDX models: one with deletion of the SMAD4 gene and the other from a KRAS mutation cell line." (PMID 40190550, 2025). "The loss of SMAD4, a critical mediator of TGF-β signaling, which occurs in nearly 50% of pancreas cancer cases, has also been modeled in vivo." (PMID 40829173, 2025). "For instance, in pancreatic cancer, PGK1 can translocate into the nucleus and participate in the regulation of gene transcription under SMAD4 mutation, thereby inducing the invasion capabilities of pancreatic cancer cells." (PMID 40534132, 2025). "Smad4/DPC4 gene inactivation is particularly frequent in pancreatic cancer, contributing to the highly invasive and metastatic characteristics." (PMID 40650134, 2025).
pancreatic cancer (continued). "In pancreatic cancer, radiomics features by [18F]FDG PET/CT can predict some genetic mutations such as KRAS and SMAD4." (PMID 40192792, 2025). "While SMAD4 mutations are known to influence disease progression in some contexts, their lack of association with survival in our cohort may reflect the multifactorial nature of pancreatic cancer prognosis and the influence of co-occurring molecular or clinical features." (PMID 40869017, 2025). "Another protein involved in pancreatic cancer initiation and progression is SMAD4, which is a crucial mediator protein in the TGF-β signaling pathway." (PMID 39361216, 2025). "In SMAD4 deletion-induced pancreatic cancers, there is an upregulation of PGK1 expression, leading to enhanced aerobic glycolysis and increased invasive behaviors." (PMID 38686046, 2024). "Previous studies have established Smad4’s role in cellular signaling pathways and its involvement in various cancers, including pancreatic cancer." (PMID 39596873, 2024). "The importance of understanding Smad4’s structure, function, and regulatory mechanisms is emphasized, given its potential prognostic value in pancreatic cancer." (PMID 39596873, 2024). "This group also reported that dMMR tumors were less likely to have mutations in traditional pancreatic cancer markers such as KRAS and SMAD4, but rather showed mutations in JAK1 and ACV2RA which correspond with microsatellite instability." (PMID 39458133, 2024). "These chromosome arms contain tumor suppressor genes frequently deleted or mutated in pancreatic cancer, such as CDKN2A and SMAD4." (PMID 39700179, 2024). "SMAD4 inactivation often occurs through homozygous deletion, highlighting its crucial role as a gatekeeper in pancreatic cancer." (PMID 39087024, 2024). "Knocking down SMAD4 in pancreatic cancer cells leads to increased radio-resistance, heightened DNA damage, genomic instability and decreased levels of key DNA double-strand break repair proteins." (PMID 38666907, 2024). "In pancreatic cancer, SMAD4 inactivation occurs in nearly half of cases, impairing its anti-tumoral function and promoting pro-tumoral activities." (PMID 38474109, 2024). "In Smad4-positive pancreatic cancer cells with KRAS activation, TGF-β induces apoptosis, thus suppressing tumor growth." (PMID 38569937, 2024). "Specifically, in pancreatic cancer, Smad4 serves as a tumor suppressor by inhibiting epithelial cell proliferation, and its loss can lead to tumor-promoting effects, illustrating the dual role of TGF-β in this malignancy." (PMID 39596873, 2024). "Further, TGFβ1 was recently shown to induce a novel complex composed of NFAT5, Smad3, and Smad4, which promotes epithelial-to-mesenchymal transition in pancreatic cancer cells." (PMID 39595620, 2024).
pancreatic cancer (continued). "Studies assessing SMAD4 expression’s prognostic significance in resected pancreatic cancer highlight its critical role." (PMID 38666907, 2024). "Specifically, the expression of SMAD4 significantly diminishes the rate of extracellular acidification and elevates the rate of oxygen consumption in pancreatic cancer, leading to metabolic reprogramming in this context." (PMID 38686046, 2024). "This miRNA is strongly overexpressed, while the SMAD4 expression is subsequently downregulated in pancreatic cancer patients." (PMID 38559560, 2024). "Further research is needed to elucidate Smad4’s role in pancreatic cancer progression and to explore innovative treatments based on this understanding." (PMID 39596873, 2024). "In contrast, the growth of SMAD4-mutant pancreatic cancer PDOs was unaffected by Noggin/A83-01 withdrawal." (PMID 39195202, 2024). "In summary, our study elucidated the pivotal role of SMAD4, a gene commonly mutated in PDAC, in attenuating PARP1-mediated DNA repair and contributing to radiotherapy resistance in pancreatic cancer." (PMID 39528473, 2024). "Next, we investigated the therapeutic efficacy of PARP inhibitors as adjuvant drugs during radiotherapy across different SMAD4 statuses in pancreatic cancer." (PMID 39528473, 2024). "It has even been shown that the addition of ectopic miR-421 to pancreatic cancer cell lines considerably reduces the SMAD4 expression in these cells, resulting in cell proliferation and cell invasion." (PMID 38559560, 2024). "Knockdown of SMAD4 in pancreatic cancer cells enhances glycolysis and diminishes mitochondrial function." (PMID 38686046, 2024). "TGF-β1 down-regulated AGR2 in pancreatic cancer cell lines, and SMAD4 was identified as a key mediator in this regulation." (PMID 38666907, 2024). "Restoring SMAD4 deletion has been observed to inhibit tumorigenic activity in pancreatic cancer cells." (PMID 38474109, 2024). "DKO cell lines formed pancreatic tumors in mice, but their histological features were distinct from SMAD4 or TGFBR2 single knockouts as they produced mixed epithelial/mesenchymal morphologies with cells expressing both E-cadherin and vimentin." (PMID 38573819, 2024). "Pancreatic cancer PDOs with wildtype SMAD4 were undetectable using IHC, because of the existence of the BMP/TGF-β-inhibiting molecules, Noggin and A83-01, in the organoid culture medium." (PMID 39195202, 2024). "Data from mouse models of pancreatic cancer have revealed that transcriptionally active p73 (TAp73) impacts the TGF-β pathway through activation of Smad4 and secretion of biglycan (Bgn)." (PMID 38255305, 2024). "Research has shown that alterations in SMAD4 are closely associated with the development of various gastrointestinal tumors, including gastric cancer, CRC, and pancreatic cancer." (PMID 39164192, 2024).